PAQR3 (progestin and adipoQ receptor family member 3)
Diseases named in the same sentence as PAQR3 in open-access papers (continued):
Sharing a sentence is not in itself a finding about the gene and the disease.
colon cancer (2 papers, 2020 to 2025). "To investigate the functional impact of PAQR3 knockdown in colon cancer cells, we successfully established stable PAQR3 knockdown (shPAQR3) and control (shCon) cell models." (PMID 40723340, 2025). "CCK8 assays subsequently confirmed the significant inhibitory effect of PAQR3 overexpression on the viability of colon cancer cells." (PMID 40723340, 2025). "We further confirmed the inhibitory effects of PAQR3/P6-55 on the growth of colon cancer cells through RNA sequencing and functional validation." (PMID 40723340, 2025). "It was found that the peptide segment P6-55, synthesized from 6 to 55 amino acids at the N-terminus of PAQR3, functions similarly to PAQR3 and effectively inhibits the growth of colon cancer both in vitro and in vivo." (PMID 40723340, 2025). "We selected two colon cancer cell lines and successfully constructed stable cell lines with both PAQR3 overexpression and knockdown." (PMID 40723340, 2025). "The identification of the PI3K-AKT signaling pathway’s role in regulating the growth of colon cancer cells provides important insights for understanding the functional mechanisms of PAQR3 in colon cancer." (PMID 40723340, 2025). "This study aims to elucidate the mechanism of PAQR3 and explore its therapeutic potential in colon cancer." (PMID 40723340, 2025). "To further investigate the functional properties of PAQR3, we explored its potential tumor-inhibitory effects by constructing PAQR3 overexpression (PAQR3-OV) and corresponding control (Con) models in colon cancer cells." (PMID 40723340, 2025). "This study explores the roles and therapeutic potential of Progestin and adipoQ receptor 3 (PAQR3) in colon cancer." (PMID 40723340, 2025). "This discovery provides new insights into the tumor-suppressive role of PAQR3 and highlights its potential as a therapeutic target for the development of precision treatments for colon cancer." (PMID 40723340, 2025). "Colon cancer is one of the leading malignant tumors worldwide, and the membrane protein PAQR3 has been identified as a tumor suppressor in multiple cancers." (PMID 40723340, 2025). "Through a series of cell proliferation and migration assays, we confirmed that both PAQR3 and the P6-55 peptide exert significant tumor-suppressive effects in colon cancer cells." (PMID 40723340, 2025). "In conclusion, our findings highlight the therapeutic potential of PAQR3/P6-55 as novel colon cancer inhibitors." (PMID 40723340, 2025). "The expression level of PAQR3 in colon cancer tissues is significantly lower than that in normal colon tissues, and this change is closely associated with the malignant degree of colon cancer." (PMID 33123538, 2020). "Furthermore, colony formation assays confirmed these results, indicating an increase in the number of colonies that were formed in both colon cancer cell lines following PAQR3 knockdown." (PMID 40723340, 2025). "Notably, this study revealed PAQR3’s inhibitory effect on the PI3K-AKT signaling pathway in colon cancer cells, thereby elucidating its potential to inhibit tumor growth." (PMID 40723340, 2025). "Furthermore, we confirmed that P6-55 exhibits functional similarities to PAQR3, effectively inhibiting the growth of colon cancer in vitro and in vivo." (PMID 40723340, 2025). "Additionally, we observed that the overexpression of PAQR3 effectively inhibited the migratory capability of colon cancer cells, further supporting its potential role in suppressing cancer progression." (PMID 40723340, 2025). "By constructing stable cell line models of PAQR3 overexpression and knockdown in two colon cancer cell lines and then performing CCK8, colony formation, and transwell migration assays, we observed that PAQR3 significantly inhibits the proliferation and migration of colon cancer cells." (PMID 40723340, 2025).
colon cancer (continued). "Finally, GSEA indicated that after PAQR3 knockdown, growth- and tumor-related pathways exhibited an upregulation trend, providing new insights and a foundation for understanding the tumor-suppressive role of PAQR3 in colon cancer." (PMID 40723340, 2025). "Given the critical role and frequent abnormal activation of the PI3K-AKT-mTOR and MAPK/ERK signaling pathways in tumors, we speculate that PAQR3 may regulate the growth of colon cancer cells by inhibiting the PI3K-AKT-mTOR pathway, the MAPK/ERK pathway, or even the Wnt pathway." (PMID 40723340, 2025). "Specifically, we selected two colon cancer cell lines—HCT116 and HCT15—and performed qRT-PCR to evaluate the efficiency of PAQR3 overexpression in these cells." (PMID 40723340, 2025). "To explore the tumor-suppressive mechanisms of PAQR3 in colon cancer, we performed RNA sequencing to compare the HCT15 stable cell line with PAQR3 knockdown with corresponding control cell lines." (PMID 40723340, 2025).
diabetes (2 papers, 2018 to 2025). "It is also found that PAQR3 knockout obviously reversed HFD-induced diabetes, fatty liver, and remarkably improved insulin resistance, strengthen energy metabolism in mice." (PMID 29930535, 2018). "All of these evidences suggested PAQR3 plays an important role in the progression of diabetes and other diabetes-related complications." (PMID 29930535, 2018).
glioma (2 papers, 2022 to 2024). A benign or malignant brain and spinal cord tumor that arises from glial cells (astrocytes, oligodendrocytes, ependymal cells). "In Acute Myeloid Leukemia, Lower-grade Glioma and Glioblastoma, Pediatric Low-grade Gliomas, Kidney Chromophobe, and Thyroid Cancer, PAQR3 expression was positively correlated with OS and DSS, while in Rectum Adenocarcinoma, PAQR3 expression was negatively correlated with OS." (PMID 38321173, 2024). "Similarly, the RKTG/PAQR3-mediated inactivation of the PI3K/AKT signaling pathway leads to the inhibition of in vitro glioma cell proliferation and attenuates in vivo xenograft tumor growth." (PMID 35805075, 2022).
Insulin resistance (2 papers, 2018 to 2025). Increased resistance towards insulin, that is, diminished effectiveness of insulin in reducing blood glucose levels. "It has been demonstrated that PAQR3 mediates insulin resistance, glucose and lipid metabolism, and inflammation." (PMID 29930535, 2018). "PAQR3, as a new tumor suppressor gene, plays a vital role in inflammation, insulin resistance, glucose and lipid metabolic disorder diseases." (PMID 29930535, 2018). "Numbers of evidence indicated that PAQR3-deficient mice are resistant to high-fat-diet (HFD)-induced obesity and hepatic steatosis, accompanied by improvement of insulin resistance and insulin signaling, which suggests that PAQR3 plays a vital role in the regulation of glycolipid metabolism." (PMID 29930535, 2018). "Considering that DN is characterized by renal inflammatory fibrosis and PAQR3 regulates insulin resistance, glycolipid metabolism, and inflammatory response, we are highly concerned whether PAQR3 can regulate diabetic renal inflammatory fibrosis, eventually contributing to DN." (PMID 29930535, 2018). "DDB2 directly interacts with progestin and adipoQ receptor 3 (PAQR3), facilitating PAQR3 ubiquitination, consequently enhancing PI3K/AKT axis signaling to ameliorate insulin resistance and mitigate retinopathy in diabetic mice." (PMID 40276708, 2025).
laryngeal squamous cell carcinoma (2 papers, 2020 to 2022). A squamous cell carcinoma that arises from the larynx. "Compared with adjacent tissues, the expression of PAQR3 in laryngeal squamous cell carcinoma (LSCC) tissues was significantly downregulated, and overexpression of PAQR3 inhibited the proliferation and invasion of LSCC cells." (PMID 33123538, 2020).
leukemia (2 papers, 2021 to 2023). A malignant (clonal) hematologic disorder, involving hematopoietic stem cells and characterized by the presence of primitive or atypical myeloid or lymphoid cells in the bone marrow and the blood. "PAQR3 (progestin and adipoQ receptor family member 3) is involved in the occurrence of many tumors as a tumor suppressor and can inhibit the proliferation of human leukemia cells and induce cell apoptosis." (PMID 38125948, 2023). "PAQR3 has bee n shown to repress human leukemia cells proliferation and induce cell apoptosis, but its role and relevant regulatory mechanism on cell proliferation and ferroptosis in ALL needs more exploration." (PMID 33955706, 2021).
lung adenocarcinoma (2 papers, 2024 to 2025). A carcinoma that arises from the lung and is characterized by the presence of malignant glandular epithelial cells. "Increased expression of PAQR3 was found to improve the OS of patients with lung adenocarcinoma." (PMID 40391162, 2025).
lung carcinoma (2 papers, 2017 to 2020). "At present, PAQR3 expression has been found to be decreased in lung cancer tissues and is significantly correlated with the pathological classification, degree of differentiation, TNM stage, and lymph node metastasis in patients with lung cancer." (PMID 33123538, 2020). "Gene set enrichment analysis (GSEA) was performed to investigate the possible mechanism through which PAQR3 is involved in the progression of lung cancer." (PMID 33123538, 2020). "The expression of PAQR3 protein was detected by immunohistochemistry in lung cancer and adjacent normal tissues." (PMID 28442015, 2017). "The expression of PAQR3 protein significantly decreased in lung cancer, indicating that PAQR3 protein plays an important role in the pathogenesis of PAQR3 in lung cancer." (PMID 28442015, 2017). "The positive expression rate of PAQR3 protein in lung cancer was lower than that in adjacent normal tissues (P < 0.01)." (PMID 28442015, 2017). "The possible physiological processes regulated by PAQR3 in lung cancer via GSEA." (PMID 33123538, 2020). "This study investigates the expression of PAQR3 in lung cancer and its clinical significance." (PMID 28442015, 2017). "Therefore, in the present study, we analyzed the expression of PAQR3 and its clinical value in NSCLC, and explored its function in the progression of NSCLC to provide a new target for molecular diagnosis and treatment of lung cancer." (PMID 33123538, 2020).
Obesity (2 papers, 2018 to 2021). Accumulation of substantial excess body fat. "PAQR3 has modulatory roles in obesity, energy metabolism, and leptin signaling." (PMID 33526009, 2021).
prostate carcinoma (2 papers, 2017 to 2022). A carcinoma that arises from epithelial cells of the prostate gland. "Thirdly, as PAQR3 is able to suppress migration of prostate cancers, the association of PAQR3 with metastasis and EMT need to be addressed in the future." (PMID 28903314, 2017). "Secondly, it will be important to further elucidate the molecular mechanisms associated with the tumor suppressive activity of PAQR3 in prostate cancers." (PMID 28903314, 2017). "Due to potential significance of PAQR3 in regulating the tumorigenicity of prostate cancers, it will be important to further explore the functions of PAQR3 in the context of prostate cancer development." (PMID 28903314, 2017). "In this study, we report that PAQR3 is able to inhibit the growth and migration of human prostate cancer cells both in vitro and in vivo." (PMID 28903314, 2017). "Our studies have provided compelling evidence that PAQR3 functions as a tumor suppressor that controls the proliferation, migration and tumorigenicity of prostate cancer cells both in vitro and in vivo." (PMID 28903314, 2017). "Consistently, the transwell assay further confirmed that the cell migration rate of these two prostate cancer cells was decreased by PAQR3 overexpression." (PMID 28903314, 2017). "We found that the phosphorylation of ERK and AKT was robustly inhibited by PAQR3 overexpression in the prostate cancer cells." (PMID 28903314, 2017). "In this study, we investigated the potential functions of PAQR3 in prostate cancer and revealed that PAQR3 inhibits cell growth, migration and tumor development of human prostate cancer cells." (PMID 28903314, 2017). "At the cellular level, PAQR3 inhibits the cell proliferation, colony formation and migration of human prostate cancer cells." (PMID 28903314, 2017). "The growth of the prostate cancer cells in the mice as measured by tumor size, tumor weight and tumor volume was significantly reduced by PAQR3 overexpression." (PMID 28903314, 2017). "We next investigated the possible function of PAQR3 on the migratory ability of prostate cancer cells." (PMID 28903314, 2017). "In contrast, the migration of the prostate cancer cells as analyzed by wound healing and transwell assays was significantly promoted by PAQR3 knockdown." (PMID 28903314, 2017). "Mechanistically, PAQR3 is able to inhibit both Ras/Raf/MEK/ERK and PI3K/AKT signaling cascades in prostate cancer cells and such inhibition likely underlies its tumor suppressive activity in these cells." (PMID 28903314, 2017). "In order to further elucidate the tumor suppressive activity of PAQR3 in prostate cancers, we next investigated the effects of PAQR3 on tumor growth using a xenograft model." (PMID 28903314, 2017). "Collectively, these data indicate that PAQR3 has a tumor suppressive activity in human prostate cancer cells and may stand out as a potential therapeutic target for prostate cancers." (PMID 28903314, 2017). "We next analyzed the effect of PAQR3 knockdown on cell proliferation of the prostate cancer cells." (PMID 28903314, 2017). "We found that the expression level of PAQR3 is significantly lower in prostate cancers than the normal tissues, indicating that PAQR3 may function as a tumor suppressor in the development of human prostate cancers." (PMID 28903314, 2017). "At the animal level, PAQR3 strongly suppresses the growth of prostate cancers in mice." (PMID 28903314, 2017). "Firstly, it needs to be determined whether the expression level of PAQR3 is altered in human prostate cancer patient samples and if there is a change, whether the change is correlated with clinical parameters of the patients." (PMID 28903314, 2017). "We investigated whether PAQR3 has a direct effect on the growth of human prostate cancer cells including PC3 and DU145 cell lines." (PMID 28903314, 2017). "It will be important to determine whether some key regulators of EMT are involved in PAQR3 regulation on migration and metastasis of prostate cancer cells." (PMID 28903314, 2017).
prostate carcinoma (continued). "We next explored whether these two signaling pathways were also affected by PAQR3 in prostate cancer cells." (PMID 28903314, 2017). "Finally, it will be of paramount significance to explore whether perturbation of PAQR3 function can be used as a new strategy to treat prostate cancers." (PMID 28903314, 2017). "However, it is currently unknown whether PAQR3 has a functional role in prostate cancer." (PMID 28903314, 2017). "Collectively, these data indicated that PAQR3 has a negative effect on the growth of human prostate cancer cells." (PMID 28903314, 2017). "As a newly discovered tumor suppressor, the potential function of PAQR3 in human prostate cancer has not been demonstrated." (PMID 28903314, 2017).
diabetic nephropathy (1 paper, 2025). "Studies have found that chicoric acid can reduce blood glucose levels and improve diabetic nephropathy by promoting the counter-regulation of PAQR3." (PMID 41372957, 2025).
diffuse large B-cell lymphoma (1 paper, 2024).
fibrosis (1 paper, 2018). the formation of excess fibrous connective tissue in an organ or tissue in a reparative or reactive process. "Mechanistically, PAQR3 activates NF-κB signaling pathway to mediate kidney inflammatory fibrosis through direct interaction with IKKβ in DN." (PMID 29930535, 2018).
hepatocellular carcinoma (1 paper, 2020). A malignant tumor that arises from hepatocytes. "In addition, overexpression of miR‐543 promoted the proliferation, migration, and invasion of hepatocellular carcinoma cells by targeting PAQR3, suggesting miR‐203a‐3p played an oncogenic role in HCC development." (PMID 32125733, 2020).
herpesvirus infection (1 paper, 2025). "Given the impact of PAQR3 knockdown on TSC22D3, we also observed that differentially expressed genes were enriched in the Herpes simplex virus 1 infection, Human T-cell leukemia virus 1 infection, Human immunodeficiency virus 1 infection, and Kaposi sarcoma-associated herpesvirus infection pathways." (PMID 40723340, 2025).
lentivirus infection (1 paper, 2015). Virus diseases caused by the Lentivirus genus. "We further analyzed the function of PAQR3 by establishing a MDA-MB-231 cell line with downregulation of PAQR3 by lentivirus infection." (PMID 25900239, 2015).
melanoma (1 paper, 2015). A malignant, usually aggressive tumor composed of atypical, neoplastic melanocytes. "PAQR3 has a suppressive function in A375 human melanoma cells that harbor an oncogenic B-Raf mutation V600E, the most common mutation in melanoma." (PMID 25900239, 2015).
neuroblastoma (1 paper, 2024). Neuroblastoma (NB) is the most common solid, extracranial childhood tumor. "Through the analysis of TCGA, UALCAN, GEO, GEPIA2, TIMER, Kaplan–Meier plotter, TISIDB and other databases, it was found that the expression level of PAQR3 changed significantly in different tumor types, and the expression level of Neuroblastoma was very high." (PMID 38321173, 2024).
osteosarcoma (1 paper, 2020). A usually aggressive malignant bone-forming mesenchymal neoplasm, predominantly affecting adolescents and young adults. "In osteosarcoma, the expression of PAQR3 was decreased and was associated with metastasis in patients." (PMID 33123538, 2020). "In addition, overexpression of PAQR3 inhibited the proliferation, migration, and invasion of osteosarcoma MG-63 cells by promoting the phosphorylation of ERK." (PMID 33123538, 2020).